IDH1 (isocitrate dehydrogenase (NADP(+)) 1)
Diseases named in the same sentence as IDH1 in open-access papers (continued):
Sharing a sentence is not in itself a finding about the gene and the disease.
astrocytomas (continued). "Furthermore, Manocha and Jain (2019), attributed the lower WT1 scores in grade II astrocytomas to the high frequency of IDH1 positivity." (PMID 32856872, 2020). "According to the updated WHO 2016 classification, 75–80% of grade II diffusely infiltrating astrocytomas have IDH1/2 mutation and 20–25% do not." (PMID 31853670, 2019). "However it is limited by the fact that only in three cancers, AML, astrocytomas and oligodendroglioma we were able to perform a comparison with biologically relevant wild-type tumors and only in AML we compared the IDH1/2 mutated tumors with the normal tissue." (PMID 31727977, 2019). "We analyzed DNA methylation data from IDH1/2 mutant acute myeloid leukemia, oligodendroglioma, astrocytoma, solid papillary breast carcinoma with reverse polarity, sinonasal undifferentiated carcinoma and cholangiocarcinoma, which clustered by their embryonal origin." (PMID 31727977, 2019). "Thus, it is likely that oligodendroglioma and astrocytoma arise from a common precursor cell, such as NSC, because they harbor the same mutation in IDH1/2, which is probably the initiating event in gliomagenesis." (PMID 30510501, 2018). "The prevalence of IDH1/2 mutations in gliomas greatly varies depending on the subtypes of tumors; about 70% of astrocytomas of WHO grade II and III carry IDH1/2 mutations, whereas other gliomas such as ependymomas of grade II or pilocytic astrocytomas of grade I do not carry IDH mutations." (PMID 30192797, 2018). "Investigating the association between IDH1 status and MMP-2 levels in grade II-III astrocytomas, patients with wildtype IDH1 tumors (wtIDH1, n = 10; mean: 106.0 ±4.0) tended to have higher MMP-2 intensity than patients with mutated IDH1 tumors (mIDH1, n = 7; mean: 97.9 ±3.2) (p = 0.17)." (PMID 28234925, 2017). "For example, instead of the previous distinction as astrocytoma, these tumours may now be classified as a diffuse astrocytoma, IDH1/2 mutant, diffuse astrocytoma, IDH1/2 wild-type or diffuse astrocytoma, or NOS." (PMID 29099032, 2017). "Direct sequencing detected one IDH2 mutation in a grade II astrocytoma and additionally six IDH1 mutations were identified not attributed to R132H mutation or from samples with missing IDH1 immunohistochemistry." (PMID 28467778, 2017). "In a prospective analysis, Wick and colleagues found that grade III astrocytomas that possessed the IDH1 mutation were associated with greater PFS regardless of the treatment." (PMID 26858939, 2016). "However, while 20 to 40% of the tumour cells from wild-type IDH1/2 astrocytomas showed strong staining for p-AKTT308, the upstream activator of mTORC1, less than 2% of IDH1R132H-mutated astrocytomas stained positively for p-AKTT308." (PMID 27624942, 2016). "In conclusion, this study clearly provided evidence that FilGAP, as well as IDH1 status, may be useful for predicting the behavior of astrocytomas." (PMID 27790861, 2016). "Maybe, oligoastrocytomas (WHO grade II/III) may be separated into two groups, genetically matching oligodendroglioma on one and astrocytoma on the other side based on the molecular information, for example, IDH1/2, 1p/19q and ATRX and so on." (PMID 26918938, 2016). "In addition, the patients with high FilGAP score and IDH1‐mt tumors had the best OS and PFS, in contrast to the patients with low FilGAP score and wild‐type (wt) IDH1 astrocytomas who had the worst prognosis." (PMID 27790861, 2016).
astrocytomas (continued). "We here identify and characterize IDH1R314C, a novel and rare mutation in IDH1 in a high grade astrocytoma which has not been reported before." (PMID 27460417, 2016). "Previously, a Dutch study revealed that IDH1 mutation was a good predictor of OS but not response to temozolomide after radiotherapy in patients with low-grade astrocytomas, which is in agreement with our findings." (PMID 26115094, 2015). "IDH1 mutation was associated with better OS in patients with oligoastrocytomas or oligodendrogliomas (p = 0.047), but not in patients with astrocytomas (p = 0.124)." (PMID 26115094, 2015). "We determined significantly different enzymatic activities for distinct IDH1 mutations and provide a selection based hypothesis for the preponderance of the IDH1R132H mutation in astrocytoma and oligodendroglioma." (PMID 24529257, 2014). "Those without mutation in either marker had only a slightly better outcome (median OS 17 months), while those with an IDH1/2 mutation alone, the signature characteristic of Grade II-III astrocytomas and Grade IV secondary GBMs, had the best outcome among the Grade IV tumors (median OS 42 months)." (PMID 24722048, 2014). "Higher IDH1 mutation rates are seen in grade II and III astrocytomas and oligodendrogliomas." (PMID 24202337, 2013). "We observed two cases of astrocytoma without IDH1 mutation presenting LOH for several markers in surgery samples (in vivo)." (PMID 21326241, 2011). "Two out of five astrocytomas presenting lack of IDH1 mutation (after the analysis of surgery sample and early cell culture sample), showed LOH of several markers." (PMID 21326241, 2011). "The absence of preoperative performance differences between diagnostic groups in our sample for most tests indicates that individuals with untreated IDH-1 mutated astrocytoma and oligodendroglioma do not present with vastly different levels of executive functioning." (PMID 41514682, 2026). "Grade 4 IDH1/2-mutant astrocytomas and grade 3 oligodendrogliomas showed positive correlations with a range of molecular alterations, while grades 2/3 in IDH1/2-mutant astrocytomas and grade 2 oligodendrogliomas were negatively correlated with nearly all of the same molecular alterations." (PMID 39164213, 2025). "Astrocytomas are the term for non-codeleted 1p19q tumors, whether or not they have an IDH1/2 mutation." (PMID 38827949, 2024). "The biological basis for the T2FMM appearance of microcysts is currently unknown, because microcysts also have been found in IDH1‐mutated, 1p/19q non‐codeleted astrocytomas and in oligodendrogliomas in dogs that do not present with the T2FMM sign." (PMID 37246729, 2023). "However, most IDH1-mutant astrocytomas eventually develop a malignant phenotype." (PMID 38012788, 2023). "Several types of cancer, including gliomas, acute myeloid leukemia, astrocytoma, and chondromas, have been found to harbor heterozygous missense mutations in the nicotinamide adenine dinucleotide phosphate (NADP+)-dependent IDH enzymes, mitochondrial IDH2 enzymes, and cytosolic IDH1 enzymes." (PMID 36286449, 2022). "All of the three tumors with IDH1/2 mutations had necrosis and microvascular proliferation, thus our cohort included four patients with GBM, IDH-wildtype, WHO grade 4 (57.1%) and three patients with astrocytoma, IDH-mutant, WHO grade 4 (42.9%) based on the WHO 2021 classification." (PMID 36077758, 2022). "In addition, there is a percentage of astrocytomas (around 30%) and oligodendrogliomas (around 10%) without IDH1/2 mutations." (PMID 32570988, 2020).
astrocytomas (continued). "AED proved to be a significant factor influencing the probability of intraoperative fluorescence, when adjusted for other potential confounders (astrocytoma/non-astrocytoma, frontal localization, dexamethasone dose, IDH1-mutation) in a logistic regression model." (PMID 31192128, 2019). "Collectively, these data indicate that IDH1/2 mutations leading to an increased methylation of H3K9 and H3K79 and decreased 5-hmC may occur in a context-dependent manner in a subset of Acute Myeloid Leukemias, oligodendrogliomas and astrocytomas." (PMID 29290954, 2017). "Therefore, the aim of this study was to characterize the genomic profile of 65 Brazilian astrocytomas, using aCGH and MSI, as well as to associate these data with the mutational status of the TERT promoter and IDH1 genes, and clinico-pathological features of the patients." (PMID 27172220, 2016). "We find that the genome-wide GBM pattern of CNAs is statistically a better predictor of astrocytoma outcome, corresponding to greater median survival time difference, proportional hazard ratio, and concordance index, than MGMT promoter methylation and IDH1 mutation." (PMID 27798635, 2016). "Notably, our study is the first to demonstrate the prognostic significance of IDH1 mutation in patients with oligodendroglioma or oligoastrocytoma, but not in patients with astrocytoma." (PMID 26115094, 2015). "Additionally, the most frequent molecular abnormalities presented in astrocytomas (LOH 10p and LOH 10q; TP 53 mutations; EGFR amplification/chromosome 7 polysomy; EGFRvIII variant; CDKN2A deletions; IDH1 mutations) were used as markers of neoplastic cells at the DNA level." (PMID 25788865, 2014). "GBMs were characterized as primarily TERT promoter mutant/IDH wildtype (73.3%), Grade II-III astrocytomas were predominantly TERT promoter wildtype/IDH mutant (73.9%), and the majority of oligodendrogliomas mainly harbored mutations in both the TERT promoter and IDH1/2 (79.3%)." (PMID 24722048, 2014). "Therefore IDH1 mutations could serve in the near future as the standard prognostic biomarkers for patients with grade II, III, and IV astrocytomas." (PMID 24511544, 2014). "The gene set includes IDH1, IDH2, BRAF, CDKN2A/B, PTEN, and NOTCH1, but misses CIC, FUBP1, ATRX, and H3-3A important for oligodendroglioma and astrocytoma diagnosis." (PMID 37908227, 2023). "In astrocytomas, a hypermethylated genomic DNA state (CpG island methylator phenotype or CIMP) in isocitrate dehydrogenase (IDH1/2) mutant tumors correlates with increased histone methylation, altered gene expression and improved patient survival." (PMID 36604386, 2023). "IDH1 expression was significantly higher in GBM IDH-wildtype (11.56 ± 0.58) compared to IDH-mutant (10.93 ± 0.43), now reclassified as grade IV astrocytoma IDH-mutant (p-value = 2.6 × 10−3)." (PMID 35877430, 2022). "The correlation between IDH1 status and FABP7 expression level in astrocytoma, oligodendrocytoma, and oligodendroglioma analyzed using TCGA database." (PMID 34716958, 2022). "Therefore, IDH1 mutation status alone is not enough to predict the prognosis of astrocytoma." (PMID 34458259, 2021). "This was addressed by performing double IF for ETNPPL and IDH1 R132H (1 oligodendroglioma) and ATRX (2 astrocytomas)." (PMID 32218467, 2020). "Brain cancer patients, with either astrocytoma, oligodendroglioma or GBM, were separated based upon their IDH1 status using ATR-FTIR serum spectroscopy." (PMID 33302429, 2020). "Based on the ranking results, four genes (RAF1, AKT3, IDH1, and FGFR1) were independent predictors of the survival status of astrocytoma patients." (PMID 31620163, 2019). "Based on the preclinical evidence, a phase 1 trial of IDH1 peptide vaccine in IDH1-mutant and 1p19q-intact grade III-IV astrocytomas has been completed (ClinicalTrials.gov NCT02454634)." (PMID 31652645, 2019).
astrocytomas (continued). "Therefore, we performed CNA profiling of 65 astrocytomas of distinct malignant grades (WHO grade I–IV) of Brazilian origin, using array-CGH and microsatellite instability analysis (MSI), and investigated their correlation with TERT and IDH1 mutational status and clinico-pathological features." (PMID 27172220, 2016). "IDH1 alterations were significantly detected in GII and GIII astrocytomas as compared to GIV tumors." (PMID 27790861, 2016). "Unbiased molecular clustering from TCGA and non-TCGA cohorts revealed 9 distinct profiles across IDH1/2-mutant astrocytoma." (PMID 39584448, 2025). "Vorasidenib, an IDH-1 and IDH-2 inhibitor improved the progression free survival (27.7 months vs. 11.1 months) compared to placebo in patients with residual or recurrent grade 2 oligodendroglioma or astrocytoma in a phase III trial." (PMID 41567539, 2025). "Amongst grade 2/3 IDH1/2-mutant astrocytomas in the non-TCGA cohort with available survival data, 8.9% of cases (20 of the 224) had a hemizygous loss of CDKN2A/B while 15.6% (19 of the 122) of grade 4 cases had a hemizygous loss of CDKN2A/B." (PMID 39584448, 2025). "In non-TCGA IDH1/2-mutant astrocytomas, CCND2 alteration (HR: 3.05), EGFR amplification (HR: 2.43), CDKN2A/B loss (homozygous or heterozygous loss, HR: 2.28), 22q loss (HR: 1.97), and PDGFRA alteration (HR: 1.92) were negatively prognostic." (PMID 39164213, 2025). "Focal amplifications were also prognostically informative in IDH1/2-mutant astrocytomas with intact CDKN2A/B within the non-TCGA cohort." (PMID 39584448, 2025). "For example, in the cluster of IDH1/2-mutant astrocytoma without ATRX alteration (cluster 6), while median overall survival was nearly 12 years, more than a quarter of tumors were grade 4." (PMID 39584448, 2025). "The unbiased clustering methods we applied to IDH1/2-mutant astrocytoma did not include any demographic, histological, or clinical information." (PMID 39584448, 2025). "These clinical and preclinical findings support the role of PDGFRA gene alterations and downstream multiple signaling pathways, including PI3K/AKT/mTOR pathway and RAS/RAF/MEK/ERK pathway, in promoting progression of not only IDH1-mutant, but also IDH2-mutant astrocytoma." (PMID 38012788, 2023). "The isocitrate dehydrogenase 1 (IDH-1) mutation, although not frequent, confers a good prognosis in histological GBM tumors; for that reason, these tumors are now classified as astrocytomas grade 4 IDH-1 mutant tumors in the new 2021 WHO classification." (PMID 36980184, 2023). "A study published last year showed that CTH is upregulated in IDH-1 mutant astrocytomas and pharmacological CTH inhibition could attenuate to some extent astrocytoma growth in immunodeficient mice." (PMID 37300955, 2023). "Accordingly, we did not detect the typical mutations in IDH1/2 and H3F3A genes in grade II astrocytoma." (PMID 36293551, 2022). "IDH-1 comparative analysis in astrocytoma was excluded because it did not meet the analysis conditions requiring there to be 30 or more samples in the group." (PMID 33391514, 2021). "Here, we report that SOX9 and OLIG1 transcription factors, which specifically label astrocytes and oligodendrocytes in the normal brain, revealed the presence of two largely nonoverlapping tumoral populations in IDH1-mutant oligodendrogliomas and astrocytomas." (PMID 33925547, 2021).
astrocytomas (continued). "NOA16 met its primary endpoints by demonstrating the safety and immunogenicity of IDH1-vac in patients with newly diagnosed WHO grade 3 and 4 IDH1(R132H)+ astrocytomas without further positive prognostic factors." (PMID 33762734, 2021). "Dividing the LGG and HGG groups by their IDH1 mutational status, statistically significant differences were observed between the control and HGG (astrocytoma grade III and IV) groups as well as the HGG IDH1-wildtype and LGG IDH1-wildtype groups (p = 0.0203 and p = 0.0178 respectively)." (PMID 33227903, 2020). "We detected that 18 genes were respectively correlated with overall survival in astrocytoma; moreover, four genes (RAF1, AKT3, IDH1, and FGFR1) were detected as dependent variables for the prediction of the survival status of astrocytoma patients and were capable to predict the survival." (PMID 31620163, 2019). "IDH1 and IDH2 mutations are generally detected in astrocytoma and oligodendroglioma but not in the GBM subtype." (PMID 31803734, 2019). "THG images of astrocytoma WHO grade II (IDH1‐mutant without 1p19q codeletion) tissue reveal atypical‐appearing astrocytes with variable pleomorphism and enlargement of nuclei, which is confirmed in the H&E images of this tissue." (PMID 31179222, 2019). "In contrast to oligodendroglioma and astrocytoma, primary IDH1/2-wt GBMs are more genetically heterogeneous and do not have mutations defining the majority of the cells within the tumor, thus they are referred to as IDH-wt." (PMID 30510501, 2018). "To obtain a representative group of IDH-mutant high-grade astrocytomas for PROX1 protein analysis, we collected the IDH1 immunopositive (mIDH1R132) and IDH-mutated 1p19q non-codeleted tumors in our TMAs." (PMID 27626492, 2016). "This difference in median survival between non-TCGA and TCGA cohorts was more pronounced for IDH1/2-mutant astrocytoma, where non-TCGA patients had a median survival of 136.8 months (range: 1.0–262.2 months), compared to 87.9 months (range: 0.1–157.1 months, P = .0002) in TCGA patients." (PMID 39164213, 2025). "Sublclonal IDH-mutant astrocytomas also have significantly better progression-free survival and OS compared to IDH-wild-type glioblastoma, which suggests that they are not simply IDH-wild-type tumors with a late IDH1 mutation in a relatively small subclone." (PMID 37324217, 2023). "We explored the relationship between the IFN-γ -associated gene scoring model and various clinicopathological factors, and found that patients with advanced tumor grade, Astrocytoma, wild-type IDH1, 1P/19Q non-co-deletion, and wild-type ATRX had significantly higher risk scores (p < 0.05)." (PMID 36712869, 2022). "Interestingly, this astrocytoma was negative for IDH1-R132H expression by IHC analysis but NGS showed the non-canonical variant IDH1-R132S usually associated with a more favorable clinical outcome." (PMID 35372034, 2022). "A more medial component centered in the superior frontal gyrus consisted of a large circumscribed rounded T1-hypointense and T2-hyperintense area with central signal suppression on FLAIR images (the “T2-FLAIR mismatch sign”) indicative of IDH-1 mutant 1p/19q non-codeleted astrocytoma." (PMID 32690110, 2020).